PSEN1 (presenilin 1)
Diseases named in the same sentence as PSEN1 in open-access papers (continued):
Sharing a sentence is not in itself a finding about the gene and the disease.
Alzheimer disease (continued). "Due to mutations in APP and genetic risk genes, such as PSEN1 and PSEN2 which alter amyloid concentrations, patients with DS are more prone to develop Alzheimer’s disease at an earlier age (30–60 years) than those with late-onset Alzheimer’s disease (≥65 years)." (PMID 37238612, 2023). "In support of this approach, hCOs with APP and PSEN1 mutations, hCOs generated from Down syndrome iPSCs, and hCOs carrying the Alzheimer disease (AD) APOE4 risk allele show AD hallmarks, including amyloid-beta accumulation and tau hyperphosphorylation." (PMID 35985329, 2022). "Remarkably, this study showed that a lentivirus-driven HDAC1::SUMO translational fusion protein could rescue the learning and memory deficits of an APP/Presenilin 1 murine model of Alzheimer's disease, suggesting that HDAC1 SUMOylation may be neuroprotective in response to Aβ accumulation." (PMID 34003109, 2021). "A small proportion of AD cases have a genetic origin, classified as Familiar Alzheimer Disease (FAD), caused by mutations in the APP, Presenilin 1 or Presenilin 2 genes." (PMID 31920626, 2019). "Besides finding the microRNAs that could regulate the critical nodes such as APP, BACE1, CD4, DCN, IL8 and PSEN1, we searched to uncover additional regulatory mechanisms of Alzheimer’s disease genes." (PMID 26784894, 2016). "Mutations in amyloid-beta precursor protein (APP), presenilin 1 and 2 (PSEN1, PSEN2) are known to cause early onset (<60 years) familial Alzheimer disease (AD)." (PMID 22312439, 2012). "In replication analyses, 21 genes showed nominal support in UK Biobank and Alzheimer's Disease Genetics Consortium (ADGC) cohorts, with eight genes (TREM2, ACADS, MFSD12, NUP210L, PIEZO2, PSEN1, SMURF2, AKAP13) supported under identical masks." (PMID 41960309, 2026). "Less than 1% of all AD cases (10% of EOAD) have early onset autosomal dominant Alzheimer disease (ADAD) with a disease-causing variant in amyloid-β precursor protein gene (APP), presenilin 1 (PSEN1) or presenilin 2 (PSEN2)." (PMID 39849058, 2025). "In Alzheimer’s disease, the thalamus and basal ganglia exhibit significant atrophy, and recent transcriptomic analyses have shown that genes such as APOE, MAPT, and PSEN1 are differentially expressed in these regions." (PMID 41142949, 2025). "In Alzheimer’s disease, CRISPR-Cas9 reduces β-amyloid deposition by knocking out APP and PSEN1 genes, alleviating neuroinflammation and improving cognitive function." (PMID 40255230, 2025). "Changes in three distinct genes—amyloid precursor protein (APP), amyloid beta (A4), presenilin 1 (PSEN1), and presenilin 2 (PSEN2)—have been pinpointed as the primary culprits behind early-onset Alzheimer’s disease (EOAD)." (PMID 38785945, 2024). "Murine models of Alzheimer’s disease (AD) based on presenilin (PSEN) genes, particularly PSEN1 and PSEN2, have also been extensively investigated for studying the pathogenesis and progression of familial Alzheimer’s disease (FAD)." (PMID 39064171, 2024). "The role in inverse comorbidity of cancer and Parkinson’s disease/Alzheimer’s disease was shown for APOE, APOC1, SQSTM1, PSEN1, and SP1." (PMID 37298337, 2023). "For Alzheimer’s disease, it has been reported that CALB1 has protective effects against the pro-apoptotic action of mutant presenilin 1 (PS-1), attenuating the increase in intracellular calcium and aiding in the prevention of impaired mitochondrial function." (PMID 36855067, 2023). "In Alzheimer’s disease (AD), excess MAM contributes to the production of amyloid-β via the accumulation of presenilin-1, an enzymatic complex processing amyloid-β." (PMID 37967220, 2023). "In the CA1 and CA3 regions of the hippocampus and temporal cortex, genes related to Alzheimer’s disease, such as the amyloid protein precursor (APP), β-secretase (BACE1), presenilin 1 (PSEN1) and 2 (PSEN2), are deregulated by ischemia." (PMID 35741821, 2022).
Alzheimer disease (continued). "Glycogen synthase kinase 3β (GSK3β), presenilin-1 (PS1), and cyclin-dependent kinase 5 also affect vesicle trafficking in Alzheimer’s disease." (PMID 36545123, 2022). "In the familial form of Alzheimer’s disease, SOCE was found to be attenuated and endogenous presenilin 1 interacted with STIM1 in the ER." (PMID 35821821, 2022). "Interestingly, the only one that is not such an endpoint is PSEN1, which is a transmembrane protein whose mutation may lead to Alzheimer’s disease." (PMID 35565454, 2022). "The M93V variant in PSEN1, so far never described, is very interesting as localized in a mutational hot spot in a critical region for the protein function, the transmembrane domain 1: in fact, the adjacent mutations C92S and V94M are associated with Alzheimer’s disease (AD)." (PMID 36570531, 2022). "Primarily, we found several aging (klotho, major vault 1, gelsolin, huntingtin, and fragile X mental retardation protein) and Alzheimer’s disease (ADAM10, apoE receptor, ChAT, APP, and PSEN1; most of these are also involved in aging) related sequences." (PMID 32449011, 2020). "This same subunit has been shown to become destabilized in Presenilin-1 knock-out (PS1KO) cells, a model of Alzheimer’s disease, leading to elevated lysosomal pH." (PMID 31039583, 2019). "In this section, we would like to draw the attention to a circumstantiated but sometimes underestimated correlation of two diseases where both presenilin-1 and Ca2+ are known contributors to disease development namely T2DM and Alzheimer’s disease (AD)." (PMID 31817135, 2019). "The resulting transgenic mouse model, Alzheimer’s disease-like pathology with APP, PSEN1, and MAPT transgenes (ADLPAPT), exhibited Aβ accumulation, NFTs, early neuronal loss in the brain, and subsequent memory impairments." (PMID 29338754, 2018). "The peptide modulated 77 genes, of which 65 are listed in the AlzBase database and include the hallmarks of Alzheimer’s disease: APP, APOE, PSEN1, and PSEN2." (PMID 28798312, 2017). "Presenilin-1(PSEN-1) and Apolipoprotein E (APOE) genes areassociated with early and late onset of Alzheimer's disease, respectively." (PMID 28767121, 2017). "Increasing evidence suggest that molecular players in Alzheimer disease, including amyloid precursor protein (APP) and presenilin 1 (PS1) and its metabolites, play a role in adult neurogenesis." (PMID 27303258, 2016). "Long noncoding RNA (lncRNA) within mRNA sequences of Alzheimer's disease genes, namely, APP, APOE, PSEN1, and PSEN2, has been analyzed using fractal dimension (FD) computation and correlation analysis." (PMID 23662159, 2013). "The long noncoding RNAs (lncRNAs) within the mRNA sequences in Alzheimer's disease genes, namely, APP, APOE, PSEN1, and PSEN2, have been analyzed in terms of fractal dimension computation and correlation analysis." (PMID 23662159, 2013). "The lncRNAs within the mRNA sequences in Alzheimer's disease genes, namely, APP or AD1, APOE or AD2, PSEN1 or AD3, and PSEN2 or AD4, have been analyzed in terms of fractal dimension computation and correlation analysis." (PMID 23662159, 2013). "Missense mutations in three different genes encoding amyloid-β precursor protein (APP, [MIM 104760]), presenilin 1 (PSEN1, [MIM 104311]) and presenilin 2 (PSEN2, [MIM 600759]) are recognized to cause familial early-onset Alzheimer disease (EO-AD; [MIM 104300])." (PMID 22044463, 2011). "In 2009, no pathogenic variants were identified in the APP, PSEN1, and PSEN2 genes in the three living patients with Alzheimer's disease, and these negative findings were also confirmed in ES." (PMID 39810256, 2025). "In Alzheimer's disease (AD), characterized by the presence of amyloid-beta (Aβ) plaques and tau protein tangles, critical genetic factors include the amyloid precursor protein (APP), presenilin 1 (PSEN1), presenilin 2 (PSEN2), and apolipoprotein E (APOE)." (PMID 39411638, 2024).
Alzheimer disease (continued). "In this study we compared cases of EOAD (without known causal mutations in APP, PSEN1 or PSEN2), Alzheimer’s disease in individuals who had DS (AD-DS), and healthy ageing disomic individuals." (PMID 37580797, 2023). "Presenilin 1 (PS1) is a central component of γ-secretase, an enzymatic complex involved in the generation of the amyloid-β (Aβ) peptide that deposits as plaques in the Alzheimer’s disease (AD) brain." (PMID 35505961, 2022). "Interestingly, MBG also downregulated the genes involved in the Alzheimer’s disease (AD) genomic profile in DSS rats, i.e., APP mRNA expression was almost two times lower, and PSEN-1 mRNA was 40% lower in DSS-MBG vs. DSS-LS rats." (PMID 35562955, 2022). "Presenilin-1 (PSEN1), a primary component of the γ-secretase complex, is mainly related to Alzheimer's disease and may be involved in the cleavage of the Notch receptor." (PMID 34335753, 2021). "NAFLD induced Alzheimer disease in wild-type mice and in mice carrying the Swedish APP protein and the Δe9 presenilin 1 mutation but lacking mouse APP protein." (PMID 34204545, 2021). "Presenilin 1 and 2 (PS1, PS2) are two highly conserved, widely expressed, multi-pass transmembrane proteins mainly known as constituents of the catalytic core of the γ-secretase complex that is involved in the pathogenesis of Alzheimer’s disease (AD)." (PMID 34440738, 2021). "Mouse models of Alzheimer’s disease commonly use the transgenic overexpression of genes involved in the production of amyloid β (APP, PSEN1/2) and/or Tau (MAPT) and many of these models have been shown to recapitulate the hyperphosphorylated tau tangles characteristic of disease." (PMID 32255788, 2020). "Finally, network analysis in MSA-C showed enrichment for β-amyloid related functional classes, including the known Alzheimer’s disease (AD) genes, APP and PSEN1." (PMID 32493431, 2020). "For example, in neurodegenerative diseases, there is a significant proportion (>10%) of monogenic families in whom the disease is caused by singular highly penetrant disease genes, e.g., LRRK2 and PRKN in Parkinson’s disease or PSEN1 and APP in Alzheimer ́s disease." (PMID 32854198, 2020). "Our results suggest a potential benefit to screening nonfamilial Alzheimer disease (AD) cases with onset before 50 y for APP, PSEN1, and PSEN2 mutations." (PMID 28350801, 2017). "In a brain of Alzheimer disease patients one can find an accumulation of beta-amyloid protein plaques which are formed from a peptide excised from APP protein by β (BACE1) and γ-secretases (PSEN1)." (PMID 26851889, 2016). "Surprisingly, targeted exome sequencing of large multiplex pedigrees with LOAD identified mutations in APP, PSEN1, and PSEN2,11, 12 indicating that rare coding sequence variants even in genes associated with early onset Alzheimer disease (AD) may account for a portion of disease risk in LOAD." (PMID 26101835, 2015). "Furthermore, in many models of Alzheimer’s disease, overexpression of mutant human APP is often combined with overexpression of mutant human presenilin 1 (PS1), which speeds up amyloidosis in double transgenic mice, compared to single APP transgenes." (PMID 26063233, 2015). "The patient carrying this variant (PSEN1 p.I168T) was diagnosed at 86 years of age, heterozygous for APOE ε4 allele (ε2ε4), presented an advanced Alzheimer's disease (Braak V), and did not report any positive family history." (PMID 25104557, 2014). "Autosomal-dominant Alzheimer disease (ADAD) is a genetic disorder that accountsfor less than 1 % of all AD cases.It is genetically heterogeneous and has been associated with mutations in theamyloid precursor protein (APP) gene or in thetwo presenilin genes (presenilin-1 and -2 or PSEN1 and PSEN2)." (PMID 23224319, 2013).
Alzheimer disease (continued). "In addition, we have shown that gene expression profiles from our mouse models of AxD are highly congruent with a transcriptomic portrait of human Alzheimer's disease, second only to the Alzheimer's APP/PSEN1 mouse in comparison with large-scale gene expression data from over 500 animal models." (PMID 40064497, 2025). "Besides, various gene mutations closely associated with mitochondrial function, including those involving amyloid precursor protein (APP), presenilin 1 (PSEN1), 46 presenilin 2 (PSEN2), apolipoprotein E (ApoE) and a disintegrin and 71 metalloprotease 10 (ADAM10), lead to Alzheimer’s disease." (PMID 33686350, 2021). "Presenilin 1 (PS1) and Presenilin 2 (PS2) are predominantly known as the catalytic subunits of the γ-secretase complex that generates the amyloid-β (Aβ) peptide, the major constituent of the senile plaques found in the brain of Alzheimer's disease (AD) patients." (PMID 33551720, 2020). "In contrast, a small subset of the familial mutations found in presenilin 1 have been shown to decrease AICD production, suggesting that AICD might not play a role in Alzheimer’s disease." (PMID 23028730, 2012). "The transmembrane presenilin (PSEN) proteins, PSEN1 and PSEN2, have been proposed to be the catalytic components of the γ-secretase protein complex, which is an intramembranous multimeric protease involved in development, cell regulatory processes, and neurodegeneration in Alzheimer's disease." (PMID 17854491, 2007). "Next, because only APOE genotyping was available in MAS, rare genetic variants associated with Alzheimer’s disease (e.g., TREM2, PSEN1, and other SNPs) were not assessed, and therefore associations between subjective concern trajectories and these genetic mechanisms could not be examined." (PMID 41374454, 2025). "In addition to the classical early onset Alzheimer’s disease (EOAD) phenotypes, PSEN1 mutations were discovered in several atypical AD or non-AD phenotypes, such as frontotemporal dementia (FTD), Parkinson’s disease (PD), dementia with Lewy bodies (DLB) or spastic paraparesis (SP)." (PMID 37176125, 2023). "Next, we assessed the transcriptome of genes of interest to Alzheimer’s disease and resistance, APOE, APP, MAPT, PSEN1, and RELN and found no notable differences across cell lines." (PMID 38571814, 2024). "Additionally, curcumin could prevent Alzheimer’s disease progression by reducing β-amyloid (Aβ) production and induce autophagy by downregulating the PI3K/AKT/mTOR signaling pathway in amyloid β precursor protein (APP)/presenilin 1 (PS1) double transgenic mice." (PMID 36232338, 2022). "This project uses fractal dimension of mRNA and coding DNA sequences (CDS) to probe the lncRNAs within the mRNAs (but not the CDS) in Alzheimer's disease genes, namely, APP or AD1, APOE or AD2, PSEN1 or AD3, and PSEN2 or AD4." (PMID 23662159, 2013). "Previously we highlighted APP and Psen1 as good candidate modifiers in these regions since they have known links to Alzheimer's disease and Tau hyperphosphorylation, however, we did not detect significant differences in expression of APP or Psen1 between C57BL/6 and BALB/c samples." (PMID 22355340, 2012).
familial Alzheimer disease (104 papers, 2006 to 2026). A degenerative disease of the brain that causes gradual loss of memory, judgment, and the ability to function socially. "In this study, we investigate how amyloid beta oligomers and familial Alzheimer's disease‐linked Presenilin 1 mutations alter the metabolism of astrocytes derived from induced pluripotent stem cells." (PMID 39696767, 2025). "This reflects the aggressive nature of PSEN1-associated familial Alzheimer’s disease (AD), known for its early onset and rapid progression." (PMID 40649976, 2025). "People carrying mutations associated with familial Alzheimer’s disease, especially PSEN1 mutations, are more commonly affected by seizures and myoclonus." (PMID 38388921, 2024). "Significantly, loss-of-function mutations in the PSEN1 gene, encoding presenilin 1, lead to early-onset familial Alzheimer’s disease." (PMID 39201569, 2024). "Mutations in the PS1 gene (PSEN1) are the most common cause of early onset familial Alzheimer’s disease (FAD)." (PMID 36555791, 2022). "Pathogenic mutations in the PSEN1 gene are an important cause of familial Alzheimer's disease, which function as the core catalytic subunit of the beta-secretase complex involved in cleavage." (PMID 36117156, 2022). "In contrast, familial Alzheimer’s disease (FAD)-linked presenilin 1 (PSEN1) mutations (M146L and M146V) increase β-catenin levels and Wnt target gene expression, resulting in pathogenic effects." (PMID 34625606, 2021). "Presenilin-1 (PSEN1) mutations cause familial Alzheimer’s disease (FAD) characterized by early age of onset (AoO)." (PMID 33319314, 2021). "We and others have reported that human stem cell-derived cortical neurons carrying mutations in PSEN1 that cause monogenic, familial Alzheimer’s disease alter production of extracellular Aβ to longer, more aggregation-prone forms of the peptide." (PMID 33543132, 2020). "We introduced the early-onset familial Alzheimer’s disease (FAD) mutation M139T into the endogenous Rat Psen1 gene and provide an initial characterization of Aβ processing in this novel rat AD model." (PMID 33076948, 2020). "Since mutations causative of early-onset familial Alzheimer disease (FAD) have been identified in the PSEN1 and PSEN2 genes, pathophysiological functions of the encoded proteins presenilin 1 (PS1) and PS2 have been extensively studied." (PMID 30823664, 2019). "PSEN1 has been proposed to act as low-conductance, passive ER Ca2+ leak channel, with mutations in the PSEN1 protein leading to disruption or abolishment of ER Ca2+ leak activity in familial Alzheimer’s disease." (PMID 31601621, 2019). "Twenty individuals with pathological mutations in presenilin 1 or amyloid precursor protein genes for familial Alzheimer's disease (FAD) were tested together with 62 healthy controls." (PMID 27085491, 2016). "Among Caribbean Hispanics, the p.Gly206Ala variant in PSEN1 was highly prevalent among familial Alzheimer's disease (AD) and at the same time was associated with highly variable onset age." (PMID 25333068, 2014). "Presenilin-1 (PS1) is a transmembrane protein first discovered because of its association with familial Alzheimer’s disease." (PMID 23259730, 2012). "Presenilin-1 is a polytopic transmembrane protein that was first discovered because of its association with familial Alzheimer’s disease." (PMID 23259730, 2012). "CTNB1_HUMAN is a known AD protein that specifically regulates PSEN1, in which gene mutations can cause elevated accumulation of beta-Amyloid (A4_HUMAN) and lead to early-onset familial Alzheimer's Disease." (PMID 19649302, 2009). "Mutations in PSEN1 cause familial Alzheimer’s disease with almost complete penetrance." (PMID 40542358, 2025). "Each FAD line contains a different mutation in the PSEN1 gene, which causes early-onset familial Alzheimer’s disease, while the isogenic controls have the same genome as their respective FAD lines, with the exception of the FAD mutation, which has been reverted back to WT." (PMID 38792645, 2024).